RUNX2 (RUNX family transcription factor 2)
Diseases named in the same sentence as RUNX2 in open-access papers (continued):
Sharing a sentence is not in itself a finding about the gene and the disease.
cleidocranial dysplasia (continued). "The effect was of greater magnitude using a truncated mouse osteocalcin promoter, p147, where 16Q and 30Q variant activity overlapped that of some RUNX2 mutations that are associated with cleidocranial dysplasia." (PMID 22912713, 2012). "Runx2 null mice have a complete loss of bone tissue and regulation of Runx2 dosage during development can result in the cleidocranial dysplasia phenotype." (PMID 21935430, 2011). "Cleidocranial dysplasia that can include the clinical features of scoliosis or vertebral malformation is caused by mutations in the transcription factor RUNX2/CBFA1." (PMID 21176156, 2010). "Effects of MAP kinase on differentiation appeared to be mediated by the RUNX2 transcription factor in that constitutively active MEK1 was able to partially rescue the cleidocranial dysplasia phenotype associated with Runx2 haploinsufficiency." (PMID 19580458, 2010). "The cleidocranial dysplasia in heterozygous Runx2-deficient mice was significantly rescued by the genetic insufficiency of GSK-3β or the oral administration of lithium chloride, a selective inhibitor of GSK-3β." (PMID 17786208, 2007). "HOXD13/HOXA13/RUNX2 condensates with expanded polyalanine mutation fail to recruit coactivators and disrupt the formation of transcriptionally active TADs, causing synpolydactyly, hand-foot genital syndrome, or cleidocranial dysplasia." (PMID 40507965, 2025). "Runx2 haploinsufficiency is linked to cleidocranial dysplasia in humans." (PMID 39467699, 2024). "Mutations in the Runx2 gene have been shown to cause cleidocranial dysplasia." (PMID 36769300, 2023). "Heterozygous loss-of-function mutations in RUNX2 lead to cleidocranial dysplasia (CCD, MIM #119600), while gain-of-function mutations result in metaphyseal dysplasia with maxillary hypoplasia with or without brachydactyly (MDMHB, MIM #156510) and nonsyndromic midline craniosynostosis." (PMID 37500953, 2023). "Indeed, intrinsically disordered regions (IDRs) in the N-terminus of the RUNX2 protein are reportedly involved in phase separation; mutations in the Runx’2 IDRs have been proposed to be involved in cleidocranial dysplasia." (PMID 36769300, 2023). "Clinical studies have revealed that a deficiency in Runx2 leads to cleidocranial dysplasia (CCD)." (PMID 37947627, 2023). "In cleidocranial dysplasia, which is caused by heterozygous loss-of-function mutations in RUNX2, patients present with delayed ossification of the cranial base, leading to midfacial hypoplasia and ‘dish-face like’ appearance, in addition to presenting generalized skeletal malformations." (PMID 35887171, 2022). "RUNX2 involves in bone formation and is linked with cleidocranial dysplasia." (PMID 35562802, 2022). "Notably, Haploinsufficiency of RUNX2 causes cleidocranial dysplasia, which is characterized by open fontanelles and sutures, hypoplastic clavicles, supernumerary teeth and short stature." (PMID 36362086, 2022). "In addition, RUNX2 loss-of-function alleles cause cleidocranial dysplasia (CDD [MIM: 119600]), a feature of which is delayed closure of the anterior fontanelle, which was reported in two of the individuals described here." (PMID 33537682, 2021). "Polymorphisms in the RUNX2 gene are associated with cleidocranial dysplasia and osteoarthritis." (PMID 34421907, 2021). "Mutations in coding regions of RUNX2 are associated with cleidocranial dysplasia in humans." (PMID 34421907, 2021). "In addition, haploinsufficiency for RUNX2 causes cleidocranial dysplasia (CCD), as characterized by open fontanels, hypoplastic clavicles, supernumerary teeth, and short stature, in both humans and mice." (PMID 32385263, 2020). "Also, Runx2 mutations in humans, that reduce the level of this gene’s functional activity, are responsible for cleidocranial dysplasia." (PMID 31546701, 2019). "Decreased Runx2 protein function causes cleidocranial dysplasia in both humans and mice." (PMID 30575813, 2018).
cleidocranial dysplasia (continued). "The Runt-related transcription factor 2 (Runx2) gene encodes the transcription factor Runx2, which is the master regulator of osteoblast development; insufficiency of this protein causes disorders of bone development such as cleidocranial dysplasia." (PMID 25244033, 2014). "Mutations in Runx2 have been identified in patients with cleidocranial dysplasia, which is a rare autosomal dominant skeletal dysplasia characterized by delayed closure of the cranial sutures, and Runx2 has been shown to regulate the expressions of type I collagen and OC." (PMID 24926875, 2014). "Cleidocranial dysplasia (Online Mendelian Inheritance in Man # 119600) is a rare genetic disorder resulting from an autosomal dominant mutation(s) or complete loss of a functional Runx2 gene copy." (PMID 23372705, 2013). "In humans, haploinsufficiency of Runx2 causes cleidocranial dysplasia." (PMID 23776632, 2013). "Deficiency in RUNX2 is associated to cleidocranial dysplasia in humans with the characteristic facial features including a prominent forehead, wide-set eyes (hypertelorism), a flat nose and a small upper jaw, showing its importance in the medio-lateral face development." (PMID 23227218, 2012). "Furthermore, germline mutations in the Runx2 gene are strongly associated with patients diagnosed with cleidocranial dysplasia, an autosomal dominant skeletal disorder." (PMID 21559363, 2011). "For example, RUNX2 function is central to regulaton of osteoblast differentiation and tooth differentiation, and lack of one of the paired RUNX2 genes in humans causes a bone disease called cleidocranial dysplasia." (PMID 21657973, 2011). "Furthermore, mutations in the Runx2 gene are found in patients with the human disorder Cleidocranial Dysplasia." (PMID 20509905, 2010). "Furthermore, hand-foot genital syndrome (caused by HOXA13 mutations) and cleidocranial dysplasia (caused by RUNX2 mutations) may share similar mechanisms." (PMID 40507965, 2025). "Notably, mutations in RUNX2 are linked to cleidocranial dysplasia, a skeletal disorder frequently accompanied by cognitive deficits, suggesting that RUNX2 and its downstream target OCN may have broader roles beyond bone development." (PMID 40337551, 2025). "We report a preterm infant with cleidocranial dysplasia (CCD), in whom the identified RUNX2 genetic variant aligns with previously reported pathogenic loci." (PMID 41030579, 2025). "RUNX2 haploinsufficiency causes cleidocranial dysplasia (CCD), a rare genetic disorder associated with skeletal dysfunction and dental abnormalities, whereas its continuous activation can result in craniosynostosis, the premature closure of cranial sutures." (PMID 41511334, 2025). "RUNX2 mutations are linked to cleidocranial dysplasia (CCD), a rare autosomal dominant skeletal disorder characterized by abnormal skeletal phenotypes." (PMID 40177069, 2025). "Autosomal-dominant loss-of-function mutations in RUNX2 cause the disease cleidocranial dysplasia (CCD), which is characterized by patent fontanelles and hypoplastic clavicles." (PMID 37432749, 2023). "In humans, Runx2 gene mutations cause cleidocranial dysplasia (CCD, OMIM#119600), a skeletal disorder with aplasia/hypoplasia of clavicles and dental abnormalities." (PMID 35652047, 2022). "Cleidocranial dysplasia (CCD) is a rare autosomal dominant skeletal dysplasia caused by runt-related transcription factor 2 (RUNX2) mutations." (PMID 35885911, 2022). "In this sense, delayed cranial suture closure phenotypes are expected in cleidocranial dysplasia (CCD) patients in which one allele of RUNX2 has loss-of-function mutations." (PMID 32788656, 2020). "Similarly, mice expressing a dominant-negative mutant of the Map2k Mek1 in mature osteoblasts exhibit hypomineralization of clavicle and calvaria, similar to cleidocranial dysplasia (CCD) seen in human patients with loss-of-function mutations in RUNX2 or mice with Runx2 haploinsufficiency." (PMID 31013682, 2019).
cleidocranial dysplasia (continued). "Cleidocranial dysplasia (CCD) is an inherited disease caused by mutations in the RUNX2 gene on chromosome 6p21." (PMID 30123273, 2018). "Haploinsufficiency of the runt-related transcription factor 2 (RUNX2) gene is known to cause cleidocranial dysplasia (CCD)." (PMID 28173761, 2017). "The development of calvaria in the newborn was retarded similar to Runx2 +/- mice, which showed cleidocranial dysplasia, but it was much less affected than in Runx2 +/- mice at 8 weeks of age, and the suture mesenchymal cell proliferation increased." (PMID 42111267, 2026). "Our findings suggest two possible mechanisms to explain the pathogenesis of reduced cranial base growth in cleidocranial dysplasia due to RUNX2 haploinsufficiency in synchondrosis chondrocytes." (PMID 40442075, 2025). "Diseases related to RUNX2 involve cleidocranial dysplasia and metaphyseal dysplasia with maxillary hypoplasia with or without brachydactyly." (PMID 41158885, 2025). "In patients with cleidocranial dysplasia, a decrease in RUNX2 expression leads to upregulation of miR-31 and downregulation of SATB2 expression, resulting in reduced osteoclast differentiation and activity, ultimately causing delayed tooth eruption." (PMID 39834384, 2024). "Mutations in the runt-related transcription factor 2 (RUNX2), which acts as an upstream regulator of OCN, result in cleidocranial dysplasia, frequently presenting as cognitive impairment." (PMID 39633709, 2024). "RUNX2-deficient osteoblasts were used in this study to mimic cleidocranial dysplasia (CCD)." (PMID 38068903, 2023). "The skeletal condition known as cleidocranial dysplasia (CCD), which affects the clavicles, teeth, and sutures of the skull, is linked to RUNX2 mutations." (PMID 37240895, 2023). "Highlighting the therapeutic implications of these findings, in utero antioxidant therapy stabilized RUNX2 and improved bone development in the Runx2+/– haplo-insufficient mouse model of human cleidocranial dysplasia." (PMID 37432749, 2023). "Runx2-haploinsufficient mice show specific skeletal abnormalities characteristic of human cleidocranial dysplasia (CCD), including persistent fontanels, delayed closure of cranial sutures, rudimentary clavicles, and dental abnormalities." (PMID 36861967, 2023). "RUNX2 deficits result in cleidocranial dysplasia, a condition involving reduced skull ossification; RUNX2 overexpression is associated to syndromic craniosynostosis." (PMID 37552321, 2023). "Cleidocranial dysplasia (CCD) is an autosomal dominant heritable skeletal disease that affects cranial sutures, teeth, and clavicles, and the putative causative gene is Runt-related transcription factor 2 (RUNX2)." (PMID 36936765, 2023). "In addition, haploinsufficiency of Runx2 had been proven to have a causal link with cleidocranial dysplasia (CCD)." (PMID 36175952, 2022). "Delayed tooth eruption occurs in patients with cleidocranial dysplasia (CCD), a runt-related transcription factor 2 (Runx2) mutation/haploinsufficiency related disease." (PMID 34356621, 2021). "Runt-Related Transcription Factor 2 (RUNX2), a gene implicated in cleidocranial dysplasia (Online Mendelian Inheritance in Man; OMIM #119600), is a crucial transcription factor of osteoblast and chondrocyte differentiation." (PMID 32850826, 2020). "Numerous studies have demonstrated that RUNX2 participates in the physiological and pathological processes of various diseases, such as cancers, asthma, cleidocranial dysplasia, and acromegaly." (PMID 31830266, 2019). "We have used the polyQ/polyA transcription factor RUNX2 as a model for studying in vivo the role of CC structures in pathological protein aggregation and dysfunction upon polyA expansion, as occurring in cleidocranial dysplasia." (PMID 24497578, 2014).
cleidocranial dysplasia (continued). "To define the relevance of polyA CCs to the in vivo aggregation and toxicity of proteins involved in human polyA-expansion diseases, we focused on the transcription factor RUNX2, the molecular mediator of cleidocranial dysplasia upon polyA expansion." (PMID 24497578, 2014). "Runx2+/− mice, a model for human cleidocranial dysplasia, showed delayed closure of the fontanelle and hypoplasia of the clavicle due to impaired bone formation, whereas Gsk-3β+/− mice had no such abnormalities." (PMID 17786208, 2007). "The cleidocranial dysplasia phenotype by the Runx2 insufficiency was significantly rescued not only by the genetic suppression of GSK-3β, but also by the oral administration of lithium chloride." (PMID 17786208, 2007). "Cleidocranial dysplasia (CCD) will happen after mutations of Runx2, and bone formation will be severely impaired after lacking or inhibiting of Runx2." (PMID 37029290, 2023). "Haploinsufficiency of RUNX2 causes cleidocranial dysplasia, but a detailed analysis of Runx2+/− mice has not been reported." (PMID 36362086, 2022). "Notably, patients with cleidocranial dysplasia (CCD) have impaired tooth eruption and RUNX2 mutations." (PMID 30216610, 2018). "Various genes (RUNX2, PLOD, EVC, GLA, APC, NEMO) have been associated with supernumerary teeth formation in several syndromes, such as Cleidocranial dysplasia, Ehlers-Danlos Type IV, Ellis-Van Creveld, Fabry disease, Familial adenomatous polyposis, and Incontinentia pigmenti." (PMID 30148467, 2018). "Ablation of Runx2 in mice results in the absence of a mineralized skeleton, and disruption of Runx2 function causes bone defects in the human disorder cleidocranial dysplasia." (PMID 24655370, 2014). "RUNX2 contains both polyQ and polyA stretches separated by a single glutamate residue, and this polyQ/polyA region is predicted to form a CC that expands with polyA elongation up to 10–12 additional alanines as observed in cleidocranial dysplasia patients." (PMID 24497578, 2014). "Homozygous deletion of Runx2 in mice results in complete absence of osteoblasts while haploinsufficiency of RUNX2 in humans cause cleidocranial dysplasia." (PMID 24865492, 2014). "Furthermore, our observations have obvious relevance to human skeletal diseases such as cleidocranial dysplasia in which the polyQ/polyA CC structure of RUNX2 is extended by polyA expansion." (PMID 24497578, 2014). "Haploinsufficiency of Runt-related transcription factor-2 (RUNX2) is responsible for cleidocranial dysplasia (CCD), a rare hereditary disease with a range of defects, including delayed closure of the cranial sutures and short stature." (PMID 36599929, 2023). "Nell-1 overexpression transgenic (CMV-Nell-1) mice partially the calvarial defects in the cleidocranial dysplasia (CCD)-like phenotype of Runx2(±) mice, whereas Nell-1 protein induced mineralization and bone formation in Runx2(±)." (PMID 36175952, 2022). "Deletion of Runx2 in mouse models causes an absence of bone formation in the developing skeleton with perinatal lethality, and various mutations in the human gene cause Cleidocranial Dysplasia." (PMID 29176792, 2017). "Cleidocranial dysplasia associated with polyA expansion in RUNX2 is, like other polyA and polyQ diseases, a dominant genetic disease, i.e. in heterozygosis, cells contain also non-polyA-expanded copies of RUNX2 produced from the normal allele." (PMID 24497578, 2014). "Targeted disruption of Runx2 in mice leads to failure of osteoblast differentiation and bone formation, and Runx2 haploinsufficiency in humans results in the skeletal disorder cleidocranial dysplasia, with a similar phenotype observed in Runx2 haploinsufficient mice." (PMID 22151997, 2011). "But a study concerning cleidocranial dysplasia points out the potential effect of citrullination in osteoblast differentiation, as PADI2 targets RUNX2 for citrullination, which stabilized RUNX2 that promotes skeletogenesis." (PMID 40170748, 2025).
cleidocranial dysplasia (continued). "Deletion of Mek1 and Mek2, kinases upstream of ERK MAPK, in osteoprogenitors (Mek1OsxMek2−/−), resulted in severe osteopenia and cleidocranial dysplasia (CCD), similar to that seen in humans and mice with impaired RUNX2 function." (PMID 31013682, 2019). "RUNX2, ALX3 and RARA are also central in multiple sequences and related to diseases in both human and mouse: cleidocranial dysplasia, frontonasal dysplasia 1 and acute promyelocytic leukemia respectively." (PMID 29161290, 2017). "Mice homozygous for a Runx2 null allele exhibit neonatal lethality and skeletal abnormalities particularly in clavicle and cranial bones, recapitulating the underdeveloped or absence of clavicles seen in cleidocranial dysplasia (OMIM: 119600) that has been associated with mutations in RUNX2." (PMID 26719974, 2015). "In many cleidocranial dysplasia (CCD) patients who were link to Runx2 deficent, however, there are no abnormal findings in the mandible, in spite of cases of condylar malformation, persistent symphysis, or a narrow coronoid process being also known." (PMID 23762831, 2013).